TSC2 (TSC complex subunit 2)
Diseases named in the same sentence as TSC2 in open-access papers (continued):
Sharing a sentence is not in itself a finding about the gene and the disease.
subependymal giant cell astrocytoma (26 papers, 2008 to 2026). A benign, slowly growing tumor (WHO grade I) typically arising in the wall of the lateral ventricles and composed of large ganglioid astrocytes. "TSC2 variants were associated with more severe phenotypes, including subependymal giant cell astrocytoma, whereas TSC1 variants typically presented with milder manifestations." (PMID 42249814, 2026). "In subject 1.14, a TSC2 c.2525del p.(Pro842Hisfs∗52) variant was identified in genomic DNA isolated from a subependymal giant cell astrocytoma (SEGA) (VAF 51%) as well as from peripheral blood (VAF 48%)." (PMID 40225170, 2023). "We compared TSC2 deficient CT-2A mouse astrocytoma cells with syngeneic normal astrocytes that were grown under identical condition in vitro." (PMID 18474106, 2008). "We show here that phosphorylation of AMPK at Thr-172 produced apoptosis in TSC2 deficient CT-2A mouse astrocytoma under 40% dietary caloric restriction, whereas less AMPK phosphorylation with no apoptosis was seen in contra-lateral normal brain." (PMID 18474106, 2008). "This is the case of tuberous sclerosis 1/hamartin (TSC1) or tuberous sclerosis 2/tuberin (TSC2) mutations occurring in subependymal giant cell astrocytomas, as well as H3 histone family member A/B (HIST1H3A/B) and activin receptor type 1 (ACVR1) mutations in diffuse intrinsic pontine gliomas." (PMID 31968687, 2020). "For example, patients with tuberous sclerosis complex (TSC), caused by mutations in the tumor suppressor genes TSC1 or TSC2 leading to mTOR hyperfunction, show heterogeneity of benign tumors and cellular dysplasia in multiple organs, including astrocytomas and cortical tubers in the brain." (PMID 27655340, 2016). "Elevated synthesis of angiogenic growth factors in our neural cell-specific in vitro model implies that mutant cells may have the ability to promote blood vessel formation to sustain the growth of TSC2-deficient astrocytomas." (PMID 27655340, 2016). "Therefore, using activator of AMPK along with glycolysis inhibitor could be a potential therapeutic approach for TSC2 deficient human malignant astrocytoma." (PMID 18474106, 2008). "The diagnosis was confirmed by DNA methylation profiling, which assigned the tumor to the methylation class “subependymal giant cell astrocytoma with TSC1/TSC2 alterations” with a calibrated score of 0.95." (PMID 39492623, 2025). "Three cases showed TSC2 missense mutations and an additional one truncating TSC1 mutation, but a diagnosis of subependymal giant cell astrocytoma was discarded in these cases." (PMID 32642724, 2020). "No TSC1 or TSC2 mutations were identified in any of the cases, suggesting that gangliogliomas are also genetically distinct from the majority of subependymal giant cell astrocytomas." (PMID 29880043, 2018). "Similarly, in the context of the IDH mutant astrocytoma, the tumor with higher AUP1 was significantly correlated with PI3K-AKT-MTOR pathway (EGFR, PDGFRA, TSC2, MTOR), and autophagy signaling (ATG4B)." (PMID 37029364, 2023). "He underwent gross total resection; the tumor pathology was consistent with subependymal giant cell astrocytoma, WHO Grade I. Germline TSC1/TSC2 gene sequencing was negative." (PMID 36980535, 2023).
kidney tumors (25 papers, 2007 to 2023). "PGAM1 was elevated in mouse kidney tumor caused by up-regulated mTOR due to Tsc2 exon 3 deletion (Tsc2del3/+) compared with its adjacent kidney tissue." (PMID 29362480, 2018). "To accelerate the rate of development of renal tumors, we treated Tsc2+- mice with ENU, an alkylating agent which causes point mutations." (PMID 19527517, 2009). "In kidney tumors from Eker rats, the loss of the second TSC2 allele is associated with loss of OGG1 expression." (PMID 18218111, 2008). "It is known that the Tsc2-/- tumors in this mouse model have constitutively activated mTOR kinase, and a similar defect in mTOR signaling is observed in brain and kidney tumors associated with TSC." (PMID 18226258, 2008). "It has been shown that the presence of a high-expressing IFN-γ allele significantly reduces the burden of kidney tumors in Tsc2+/- mice relative to that of Tsc2+/- mice with normal IFN-γ levels." (PMID 17986349, 2007). "Similar results were seen in Tsc2-deficient 105K kidney tumor cells." (PMID 36869048, 2023). "Interstitial deletion has been reported as a mutational signature of radiation exposure in multiple animal models including medulloblastoma of Ptch1 heterozygous mice and kidney tumors of Tsc2 heterozygous Eker rats." (PMID 36662808, 2023). "Further, we performed transcriptional profiling on TSC2-deficient RA cell models and discovered that these recapitulate some of the features from TSC patient kidney tumors compared to normal kidneys." (PMID 35359406, 2022). "Tetracycline-dependent conditions and overexpression of Tsc2 inhibited the proliferation of an Eker rat-derived kidney tumor cell line." (PMID 36362447, 2022). "Animals were subjected to a tumor challenge with LB1 Tsc2–/– kidney tumor cells and subsequently treated with CAR transduced T cells." (PMID 34806651, 2021). "Rapamycin + doxycycline combination was tested only in the TSC2 KO kidney tumour model, and we examined this among other rapalog combinations in glioma models." (PMID 34360785, 2021). "The relationship between TSC1/TSC2 complex and STAT3 was further confirmed in vivo by assessing the protein and mRNA levels of STAT3 in renal tumors and adjacent normal renal tissues from Tsc2+/- mice." (PMID 31949495, 2020). "Recent published data from our laboratory show that significant inhibition of mTOR by rapamycin and activation of AMPK by AICAR in several kidney tumor cells isolated from TSC2+/− mouse model." (PMID 30250638, 2018). "Fresh primary cells isolated from normal (TSC2+/−) and kidney tumor (TSC2−/−) tissues of mice were used to confirm the effect of treatment with drug combinations versus single drug alone." (PMID 30250638, 2018). "In this study, we identified mTOR as a stimulator of PGAM1 expression in cell lines, Tsc2 mutant mouse kidney tumor sample and human NSCLC tissues." (PMID 29362480, 2018). "The gene’s genomic location and involvement in renal tumorigenesis in the rat make Tsc2 a good candidate for the AIR renal tumor locus." (PMID 24148528, 2013). "We also investigated age related kidney tumor progression and compared three different rapamycin treatment schedules in cohorts of A/J Tsc2+/- mice." (PMID 20146790, 2010). "In order to understand the progression of kidney tumor growth in A/J Tsc2+/- mice, data was collected at different time points." (PMID 20146790, 2010). "Since the brain, skin, and kidney tumors associated with TSC are vascular and TSC2 loss is associated with increased levels of HIF and VEGF in cultured cells, VEGF is a potential target for TSC treatment." (PMID 20146790, 2010). "The dual PI3K/mTOR inhibitor (NVP-BEZ-235) was used to treat ENU-accelerated kidney tumors in the Tsc2+/- mouse." (PMID 20146790, 2010). "Here, we explore the potential benefit of the mTORC1 inhibitor RAD001 (everolimus) in comparison to a dual pan-class I PI3K/mTOR catalytic inhibitor NVP-BEZ-235 in the therapy of Tsc2 mouse kidney tumors." (PMID 19527517, 2009).
kidney tumors (continued). "Kidney tumor growth in Tsc2+- mice follows a variable though predictable pattern with an effect of strain on tumor severity, (unpublished)." (PMID 19527517, 2009). "Specifically, we investigated the efficacy of rapamycin and rapamycin plus IFN-g using a dosing schedule that included a prolonged duration of weekly maintenance therapy using the Tsc2+/- kidney tumor model." (PMID 19368729, 2009). "We explored the potential benefit of mTORC1 inhibition with RAD001 in the ENU-accelerated Tsc2+- kidney tumor model." (PMID 19527517, 2009). "Here, we examine the efficacy of a prolonged maintenance dose of rapamycin in Tsc2+/- mice with TSC-related kidney tumors." (PMID 19368729, 2009). "Using ENU to enhance Tsc2+- kidney tumor development, both RAD001 (10 mg/kg PO 5 d/week) and NVP-BEZ235 (45 mg/kg PO QD) had equivalent effects in suppressing tumor development during a 4 week treatment period, with a 99% reduction in tumor cell mass." (PMID 19527517, 2009). "In a mouse genetic study, the frequency of kidney tumors was dramatically reduced in Tsc2+/- mice engineered to express high levels of endogenous IFN-γ." (PMID 17986349, 2007). "Rapamycin did not induce Mapk13 expression in TSC2-deficient mouse kidney tumor cell lines, indicating the lack of mTORC1 and m6A-dependent MAPK13 regulation mechanisms in mice." (PMID 37599001, 2023). "In addition, miR-125b-5p expression was reduced in renal tumor tissues as compared to the adjacent normal renal tissues from Tsc2+/- mice." (PMID 31949495, 2020). "When rapamycin dosing schedules were compared in A/J Tsc2+/- cohorts, we observed a 66% reduction in kidney tumor burden in mice treated daily for 4 weeks, an 82% reduction in mice treated daily for 4 weeks followed by weekly for 8 weeks, and an 81% reduction in mice treated weekly for 12 weeks." (PMID 20146790, 2010). "We have previously used Tsc2+/- mice in a C57BL/6 mixed strain to show that mTOR inhibitor treatment reduces kidney tumor severity, to investigate the timing of mTOR inhibitor treatment, and to show that addition of prolonged weekly maintenance rapamycin treatment was extremely effective." (PMID 20146790, 2010). "Here we assessed the possibility that combined PI3K-AKT-mTOR blockade with NVP-BEZ235 could lead to a better therapeutic outcome in this Tsc2+- kidney tumor model." (PMID 19527517, 2009). "The Tsc2+/- mouse is genetically similar to most humans with TSC, and they develop age-related kidney tumors that mimic important aspects of TSC-related kidney disease." (PMID 19368729, 2009). "Concurrently, the current literature showed the presence of mTORC1 pathway alteration (TSC1/TSC2/mTOR/RHEB) in a number of recently described renal tumors in patients without TSC mutations (i.e., in sporadic tumors in patients without germinal mutation of TSC1 or TSC2)." (PMID 35203531, 2022).
autism spectrum disorder (19 papers, 2012 to 2026). A spectrum of developmental disorders that includes autism, and Asperger syndrome. "Mutations in the human TSC1 and TSC2 genes are often attended with comorbid phenotypes associated with autism spectrum disorders (ASDs)." (PMID 35857265, 2022). "Here we apply multi-electrode array-based assays to study the effects of TSC2 loss on neuronal network activity using autism spectrum disorder (ASD) patient-derived iPSCs." (PMID 33076974, 2020). "Tuberous sclerosis complex related genes such as Tsc1 and Tsc2, which are upstream modulators of mTOR, are also associated with autism spectrum disorder and epilepsy." (PMID 32424120, 2020). "We found that Trc plays a role in synapse development downstream of Tsc2, which has been strongly implicated in Autism Spectrum disorders." (PMID 26393506, 2015). "TSC2 is one of the key regulators of the MTOR pathway, and is implicated in autism spectrum disorder." (PMID 36239373, 2022). "Autism spectrum disorders (ASD) are associated with mutations of chromodomain-helicase DNA-binding protein 8 (Chd8) and tuberous sclerosis complex 2 (Tsc2)." (PMID 34497307, 2021). "Tuberous sclerosis complex (TSC), a multi-system genetic disorder often associated with autism spectrum disorder (ASD), is caused by mutations of TSC1 or TSC2, which lead to constitutive overactivation of mammalian target of rapamycin (mTOR)." (PMID 33863288, 2021). "Tuberous sclerosis complex (TSC) is an inherited neurocutaneous disorder caused by mutations in TSC1 or TSC2 genes, with patients often exhibiting neurodevelopmental (ND) manifestations termed TSC-associated neuropsychiatric disorders (TAND) including autism spectrum disorder (ASD)." (PMID 37034588, 2023). "It is also unclear whether the pathway network also plays a critical role in impaired social behaviors in autism spectrum disorders not caused by Tsc1 and Tsc2 mutations." (PMID 36732866, 2023). "It is unclear whether the signaling pathway also plays a critical role in autism spectrum disorders not caused by Tsc1 and Tsc2 mutations." (PMID 36732866, 2023). "A module enriched for immune genes and glial markers has been observed in autism spectrum disorder (ASD) human post-mortem brain tissue, and immunity response-related pathways were perturbed in Fmr1KO and Tsc2+/− murine cerebellum." (PMID 26697163, 2015).
fragile X syndrome (18 papers, 2013 to 2024). A genetic syndrome caused by mutations in the FMR1 gene which is responsible for the expression of the fragile X mental retardation 1 protein. "Common examples are fragile X syndrome (FXS) caused by a mutation in the FMR1 gene and tuberous sclerosis complex (TSC) caused by a mutation in TSC1 and TSC2 genes." (PMID 33450950, 2021). "The mTOR signaling pathway is a convergent pathway that is disturbed by genetic variations in the TSC1 and TSC2 (TSC), PTEN (Bannayan-Riley-Ruvalcaba syndrome, Lhermite-Duclos syndrome, and Cowden syndrome), FMRP (fragile X syndrome), and NF1 (neurofibromatosis type 1) genes." (PMID 36732866, 2023).
Uterine leiomyoma (18 papers, 2010 to 2024). The presence of a leiomyoma of the uterus. "This growth is linked to the spread of TSC2-deficient uterine leiomyoma cells to the lungs and the development of pulmonary LAM." (PMID 38877584, 2024). "Estrogen plays a significant role in the spread of TSC2-deficient uterine leiomyoma cells to the lungs and the production of pulmonary LAM." (PMID 38877584, 2024). "In another study, a link among loss of TSC2, activation of mTORC1, and uterine leiomyomas was established with the Eker rat, which lacks one of the Tsc2 alleles." (PMID 34395438, 2021). "Our recent study reported that xenograft tumors of Tsc2-deficient rat uterine leiomyoma-derived ELT3 cells became resistant to rapamycin treatment." (PMID 32807195, 2020). "We performed quantitative PCR (qPCR) and Western blot using TSC2-deficient ELT3V and TSC2-addback ELT3T cells derived from Eker rat uterine leiomyoma." (PMID 36220392, 2022). "Previous studies including ours have shown that estrogen increases ERK1/2 phosphorylation in TSC2-deficient LAM-derived cells and rat uterine leiomyoma-derived ELT3 cells." (PMID 32078667, 2020). "To the end, we developed a rapamycin-resistant Tsc2-null cell line (ELT3-V3R) based on Tsc2-null ELT3 cells (Eker rat uterine leiomyoma, or ELT3-V3)." (PMID 30266942, 2018). "The expression of PGAM1 was suppressed by either rapamycin or ectopic expression of human TSC2 cDNA in Tsc2-null Eker rat uterine leiomyoma cell line (ELT3)." (PMID 29362480, 2018). "We have previously discovered that estrogen promotes the survival and lung colonization of intravenously injected TSC2-null rat-uterine leiomyoma-derived ELT3 cells in our preclinical mouse model of LAM." (PMID 28410230, 2017). "ELT3 cells are derived from an Eker rat uterine leiomyoma that are Tsc2-null (referred to as ‘ELT3-V3’)." (PMID 28415776, 2017). "Next, we utilized Tsc2-null mouse embryonic fibroblasts and ELT3 cells (Tsc2-null cells from an Eker rat uterine leiomyoma), which are established cellular models of TSC compared to HEK293 and A549 cells, which express TSC2." (PMID 23555865, 2013). "The MEK1/2 inhibitor was used to treat estrogen induced tumors derived from Tsc2-null uterine leiomyoma cells." (PMID 20146790, 2010). "Phase-contrast microscopy showed rapamycin slowed the growth of TSC2-deficient cells without inducing the death of TSC2-deficient patient-derived cells, rat uterine-leiomyoma-derived cells, or Tsc2−/− MEFs." (PMID 32807195, 2020). "In this study, utilizing human pulmonary LAM specimens and cell culture models of TSC2-deficient LAM patient-derived and rat uterine leiomyoma-derived cells, we tested the hypothesis that estrogen promotes the growth of mTORC1-hyperactive cells through pyruvate kinase M2 (PKM2)." (PMID 32078667, 2020). "TSC2-positive and TSC2-negative mouse embryonic fibroblasts (MEF), 323-TSC2-positive and 323-TSC2-null MEF and Eker rat uterine leiomyoma (ELT3) cells were treated with doxycycline or rapamycin alone, or in combination." (PMID 26282580, 2015).
renal cell carcinoma (17 papers, 2008 to 2025). "Tfe3-gene fusions can be causal for renal cell carcinomas, which also occur in tuberosclerosis due to mutations in Tsc1 or Tsc2 and in Bird-Hogg-Dubé (BHD) syndrome due to Flcn mutations." (PMID 23582324, 2013). "Loss of TSC2 is a key event in many types of human cancer: germline inactivating mutations of TSC2-affected patients have an increased risk of developing renal cell carcinoma." (PMID 24649216, 2013). "Loss of heterozygosity (LOH) at the TSC2 locus has been detected in TSC-associated renal cell carcinoma (RCC) and in RCC in the Eker rat." (PMID 18218111, 2008). "Loss of heterozygosity (LOH) at TSC2 locus has been detected in TSC-associated renal cell carcinoma (RCC)." (PMID 18218111, 2008). "Genes that were differentially expressed between the Low iAs/ Low TCE combination and the two individual treatment groups were over-represented in genes associated with two tumor suppressor genes (Tsc2 and Vhl) known to be involved with human renal cell carcinoma." (PMID 30898898, 2019). "Similarly, we identified 1 TSC1 splicing variant (renal cell carcinoma), 1 TSC1 nonsense mutation (anaplastic thyroid cancer), 1 TSC1 missense mutation (sarcoma) and 1 TSC2 missense mutation (angiosarcoma)." (PMID 26859683, 2016). "Given that heterozygous loss of TSC1 is common in renal cell carcinoma (>30%), TSC1 and TSC2 may be screened as predictive biomarkers of everolimus in renal cell carcinoma patients who progressed on VEGF-targeted therapy." (PMID 26859683, 2016). "Genomic studies identifying the genes for kidney cancer, including the VHL, PBRM1, MET, FLCN, fumarate hydratase, succinate dehydrogenase, TSC1, TSC2, and TFE3 genes are known to play role in renal cell carcinoma development." (PMID 35709632, 2022). "There was a recent report of renal cell carcinoma patients with extended benefit from mTOR inhibitor showed that TSC1 and TSC2 offer explanation for treatment response." (PMID 26859683, 2016). "Loss of heterozygosity (LOH) at the TSC1 or TSC2 loci has been detected in TSC-associated hamartomas and renal cell carcinoma (RCC) as well as in sporadic tumors of non-TSC patients." (PMID 19265534, 2009).